MIR6515 (microRNA 6515)
Synonyms: hsa-mir-6515; mir-6515
Gene: MicroRNA gene on chromosome 19 (12,940,484 to 12,940,540, forward strand). Ensembl gene ENSG00000274417.
Homologues: Orthologues: chimpanzee MIR6515 (100% identical).